LINC01882 (long independently transcribed non-coding RNA 1882)
Gene: Long non-coding RNA gene on chromosome 18 (12,739,486 to 12,776,143, reverse strand). Ensembl gene ENSG00000260302.
Diseases named in the same sentence as LINC01882 in open-access papers:
LINC01882 is named in the same sentence as 1 disease in open-access papers, as found by Europe PMC text mining. Sharing a sentence is not in itself a finding about the gene and the disease.
LINC01882 shares sentences with these, for which no sentence is quoted: type 1 diabetes (1 paper).